OR10J4 (olfactory receptor family 10 subfamily J member 4 (gene/pseudogene))
Description:
Odorant receptor.
Synonyms: OR10J4P; OST717
Gene: Protein-coding gene on chromosome 1 (159,432,204 to 159,433,138, forward strand). Ensembl gene ENSG00000249730.
Subcellular location: Cell membrane
Pathways (Reactome):
Sensory Perception: Expression and translocation of olfactory receptors
Homologues: Orthologues: pig OR10J4 (59% identical), rabbit OR10J4 (59% identical), guinea pig OR10J4 (59% identical), dog OR10J4 (51% identical). Paralogues in human: OR10J3 (50% identical), OR10J1 (45% identical), OR10J5 (42% identical), OR10K1 (38% identical), OR10K2 (37% identical), OR10R2 (37% identical), OR10Z1 (37% identical), OR10T2 (35% identical), OR4E1 (33% identical), OR4M1 (32% identical), OR2A5 (32% identical), OR4A47 (32% identical), and 116 more.